TNF (tumor necrosis factor)
Diseases named in the same sentence as TNF in open-access papers (continued):
Sharing a sentence is not in itself a finding about the gene and the disease.
vaginitis (3 papers, 2019 to 2025). A non-infectious or infectious inflammatory process affecting the vagina. "GV infection caused vaginitis, increasing uterine weight and TNF-α, IL-6, and RANKL levels, along with increasing the number of NF-κB+ and TNF-α+ cells in the vagina." (PMID 40284791, 2025). "Previous studies have shown that proinflammatory cytokines such as TNF-α, IL-1β, and IL-6 are increased in the vagina of women with vaginitis and are associated with the severity of vaginitis." (PMID 39941110, 2025). "In the murine model of vaginitis, the concentration of TNF-α in the Ca group increased to nearly double the concentration in the WT group, with the PAE evidencing the ability to reduce the TNF-α concentration to normal levels." (PMID 31333606, 2019). "Vaginal exposure to gEVs increased the expression of proinflammatory cytokines including TNF-α and RANKL in mice with or without OV by activating NF-κB signaling, similar to the effect of GV infection, leading to vaginitis." (PMID 40284791, 2025).
vascular occlusion (3 papers, 2014 to 2025). "The TNFα-308A allele by itself has also been associated with vascular occlusion and increased production levels of TNF-α." (PMID 24600322, 2014).
vascular tumor (3 papers, 2021 to 2023). "In addition to OPN, our results showed down-regulations of other genes in several signaling pathways including PI3K-Akt signaling, ECM-receptor interaction and TNF signaling in vascular tumor cells after autophagy blockade." (PMID 36813768, 2023).
Wilms tumor (3 papers, 2016 to 2020). An embryonal neoplasm characterized by the presence of epithelial, mesenchymal, and blastema components. "USP54 is a ubiquitin-specific peptidase that activates the TNFα-NF-κB pathway, and the upregulation of this gene family has been linked to both lung and pancreatic cancers, as well as to Wilms' tumors." (PMID 26527318, 2016). "Based on the anti-tumor activity observed in that patient with Wilms tumor, a phase II trial evaluated the combination of TNF and dactinomycin in patients with relapsed or refractory Wilms tumor." (PMID 31847387, 2019). "Recombinant TNF has been studied in combination with dactinomycin in a phase I trial in 21 patients with refractory malignancies, including sarcoma and Wilms tumor." (PMID 31847387, 2019). "Therefore, the upregulation of heme and ROS due to a decreased HO activity increases pre-adipocyte differentiation, as well as adipogenesis and the release of inflammatory adipokines such as nephroblastoma overexpressed gene (NOV), tumor necrosis factor-α (TNFα), and Interleukin-6 (IL-6)." (PMID 32751794, 2020).
Wilson disease (3 papers, 2006 to 2024). A very rare inherited multisystemic disease presenting non-specific neurological, hepatic, psychiatric or osseo-muscular manifestations due to excessive copper deposition in the body. "Compared with controls, in patients with Wilson disease, there was a significant increase in plasma of T helper (Th) 1 cells (IL-2, TNF-α, and TNF-β), Th2 cells (IL-5, IL-10, and IL-13), and Th17 (IL-23) (p < 0.05)." (PMID 38928368, 2024). "Compared with controls, in patients with Wilson disease, there was a significant increase of plasma of T helper (Th) 1 cells (IL-2, TNF-α, and TNF-β), Th2 cells (IL-5, IL-10, and IL-13), and Th17 (IL-23) (p < 0.05)." (PMID 38731973, 2024).
abnormal glucose tolerance (2 papers, 2021 to 2022). "The level of TNF-α in patients with abnormal glucose tolerance increases significantly; IL-6 can control the signal transduction of insulin receptor and reduce insulin sensitivity." (PMID 35399678, 2022). "It has been demonstrated that the increased level of blood glucose promotes a sharp increase in the concentrations of inflammatory cytokines, such as interleukin-6, tumor necrosis factor α, and interleukin-18, and this effect was more pronounced in subjects with abnormal glucose tolerance." (PMID 35059413, 2021).
actinic keratosis (2 papers, 2013 to 2021). A precancerous lesion of the skin composed of atypical keratinocytes. "We therefore propose that NF-κB activation in the absence of additional oncogenic events can promote TNF-dependent, actinic keratosis-like dysplasia and TNF-independent, KAs upon chemical carcinogensis." (PMID 23977171, 2013).
acute B lymphoblastic leukemia (2 papers, 2024 to 2025). "Wang J have demonstrated that patients with refractory/relapsed acute B lymphoblastic leukemia (B-ALL) exhibit a significant increase in TNF-α levels following CAR-T cell therapy, with peak serum levels correlating with CRS severity." (PMID 40536724, 2025).
Acute hepatic failure (2 papers, 2017). "Our findings show that EV isolated from bone marrow‐derived MSC can protect hepatocytes from apoptosis, reduce biochemical and histological hepatic injury, and enhance survival following d‐galactosamine/TNF‐α induced acute hepatic failure in mice." (PMID 28213967, 2017). "Among them, the acute hepatic failure always leads to systemic inflammation through the release of pro-inflammatory cytokines, such as tumor necrosis factor-α (TNF-α), interleukin (IL)-1β, and IL-6, which is an intractable disease with high mortality rates." (PMID 28594379, 2017).
acute laryngitis (2 papers, 2021 to 2024). An acute inflammatory process affecting the larynx. "Multivariate logistic regression analysis showed that the tumor necrosis factor-alpha, interleukin (IL)-4, IL-6, IL-17, and interferon-gamma levels were risk factors for acute laryngitis complicated by laryngeal obstruction." (PMID 39969319, 2024). "Multivariate logistic regression analysis indicated that TNF-α, IL-4, IL-6, IL-17, and IFN-γ were risk factors for the efficacy of treatment in children with acute laryngitis and laryngeal obstruction after adjustment for confounders, such as age and gender." (PMID 39969319, 2024).
acute pyelonephritis (2 papers, 2017 to 2023). "Yet, in those studies, the CRP and TNF-α values were similar (11.2 mg/dL and 35.0 pg/mL, respectively) in the patients before and 24 h after the acute pyelonephritis treatment to those observed in Phase 1 of our study." (PMID 37896187, 2023). "For example, in non-pregnant women with acute pyelonephritis, the plasma concentrations of the pro-inflammatory cytokines IL-6 and IL-8, TNF-α, and protein C reactive (CRP) can reach from 2 to 75 times the concentrations in healthy pregnant and non-pregnant women." (PMID 37896187, 2023).
acute stress disorder (2 papers, 2025). "We were unable to show changes in the circulating concentrations of IL10, IL6, and TNFα after stress, as previously reported in health volunteers, and for IL6 in patients with post‐traumatic stress disorder undergoing stress." (PMID 40584280, 2025).
acute-on-chronic liver failure (2 papers, 2013 to 2025). Acute-on-chronic liver failure (ACLF) is an extreme condition during the natural history of chronic HBV infection, with a relatively high short-term mortality. "Furthermore, the levels of pro-inflammatory cytokines such as IL-6 and TNF were reduced in patients with acute-on-chronic liver failure." (PMID 41464873, 2025). "Elevated levels of TNF-α are observed in both the serum and hepatocytes of patients with chronic HBV, and TNF-α expression is markedly upregulated in acute-on-chronic liver failure in chronically HBV-infected patients." (PMID 23606869, 2013).
adolescent idiopathic scoliosis (2 papers, 2015 to 2025). A scoliosis with no known cause arising in adolescent. "Therefore, the plasma level of TNF-α in adolescent idiopathic scoliosis patients at day 2 following orthopedic surgery may be a predictor for the incidence of early POCD." (PMID 25780449, 2015).
Adrenal Tumors (2 papers, 2010 to 2022). "A dedicated role for the intra-adrenal TNF-alpha pathway has also been proposed based on its presence in adrenal cell lines and adrenal tumors." (PMID 36614027, 2022). "The peripheral blood levels of TNF α and its soluble receptors were studied in 39 patients with malignant and benign adrenal tumors treated by adrenalectomy." (PMID 20640152, 2010). "However, to confirm practicality of the evaluation of TNF α and its soluble receptors in differential diagnosis in patients with adrenal tumors, a larger study group is needed." (PMID 20640152, 2010). "The role of the soluble receptors of TNF α in the pathogenesis of adrenal tumors is unknown." (PMID 20640152, 2010). "However, the study on the serum concentration of tumor necrosis factor α (TNF α) and its soluble receptors (TNF α R1 and TNF α R2) have not been performed in patients with adrenal tumors so far." (PMID 20640152, 2010).
Ageusia (2 papers, 2023 to 2024). A rare condition that is characterized by a complete loss of taste function of the tongue. "The serum concentrations of inflammatory markers (IL-1β, TNF-α, and CRP) were higher in subjects with ageusia/hypogeusia than in subjects with normogeusia, but without any statistical significance." (PMID 36675526, 2023).
alcohol addiction (2 papers, 2015 to 2024). "The authors suggested that a high level of TNF-α indicates the longevity and severity of alcohol addiction." (PMID 39063550, 2024). "The functional enrichment analysis was conducted to unravel the mechanisms by which zonisamide affects alcohol addiction, specifically in relation to APAF-1 and TNF-α." (PMID 39063550, 2024). "TNF, NF-κB, and ERK1/2 were present as highly interconnected genes for alcohol addiction (103, 86, and 62 edges, respectively)." (PMID 26044620, 2015). "This study investigated the effects of zonisamide treatment on cerebellar tissues in an experimental alcohol addiction (AA) model and its potential mechanisms of action, particularly regarding apoptotic protease activating factor-1 (APAF-1) and tumor necrosis factor-alpha (TNF-α) expression." (PMID 39063550, 2024).
algodystrophy (2 papers, 2008 to 2022). "In an earlier study, levels of the proinflammatory cytokines TNF-α and IL-6 are higher in blisters fluid from the complex regional pain syndrome type 1 (CRPS1) side obtained at 6 and 30 months (median) after the initial event." (PMID 18596918, 2008). "Patients with algodystrophy present an amplified and persistent activation of the innate immune system, with subsequent proliferation of keratinocytes and release of proinflammatory cytokines including interleukin (IL)-6, IL-1β, and tumor necrosis factor-α (TNF-α)." (PMID 36120194, 2022).
amnesia (2 papers, 2018 to 2022). Pathologic partial or complete loss of the ability to recall past experiences ( AMNESIA, RETROGRADE) or to form new memories ( AMNESIA, ANTEROGRADE). "Notably, the high levels of pro-inflammatory cytokines (TNF-α and MPO) and inflammatory mediator (NO) were detected in the brain of amnesia mice induced by scopolamine." (PMID 29755345, 2018).
Anaplasma phagocytophilum infection (2 papers, 2019 to 2024). "Anaplasma phagocytophilum infection leads to the upregulation of pro-inflammatory cytokines TNF-α, IL-1, MIP-2, and IL-6." (PMID 39770719, 2024).
and subcutaneous tissue disorders (2 papers, 2023 to 2025). "Adalimumab-related nervous system disorders and skin and subcutaneous tissue disorders were significantly higher than the disorders of the other four TNFα inhibitors." (PMID 37554981, 2023).
androgenetic alopecia (2 papers, 2019 to 2025). "We detected the level of TNF-α associated with androgenetic alopecia in the dorsal skin of androgenetic alopecia mice." (PMID 40521098, 2025). "Treatment with murine EX104 significantly reduced the level of TNF-α in the dorsal skin of androgenetic alopecia mice." (PMID 40521098, 2025).
antisynthetase syndrome (2 papers, 2014 to 2017). Antisynthetase (AS) syndrome is a clinically heterogeneous form of idiopathic inflammatory myopathy characterized by myositis, arthralgia, Raynaud phenomenon, mechanic hands, interstitial lung disease (ILD), and serum autoantibodies to aminoacyl transfer RNA synthetases (anti-ARS). "Between the 20 cases examined herein, one developed a subset of DM/PM called antisynthetase syndrome after the introduction of anti-TNF-α therapy." (PMID 24600322, 2014).
aortic valve disease (2 papers, 2018 to 2026). "Several cytokines relevant to aortic valve disease were found to be increased in pRb cKO mice, including TNFα and IL-17." (PMID 29304157, 2018).
arboviral disease (2 papers, 2020 to 2023). "On the other hand, these drugs may reduce the intensity of inflammation by blocking cytokines, such as TNF, involved in the pathophysiology of severe forms of arbovirus infections." (PMID 32695184, 2020).
arterial disease (2 papers, 2022). "Concomitant arterial disease in mixed venous-arterial ulcers did not influence the levels of EGF, FGF-2, IL-1α, IL-1β, IL-6, PDGF, TGF-β1 and TNF-α in one study." (PMID 35742965, 2022).
artery stenosis (2 papers, 2022 to 2024). "It was suggested that SAH, IL-1β, Hcy, TNF-α, BDNF were positively correlated with the number of coronary artery stenosis vessels(r = 0.421, 0.533, 0.301, 0.265, 0.678, P = 0.016、0.009、0.023、0.036、0.004)." (PMID 35282820, 2022). "High-mobility group box protein 1 (HMGB1) and pro-inflammatory cytokines such as tumor necrosis factor-α (TNF-α) and interleukin-1β (IL-1β) in the cortex and hippocampus of CCH mice induced by bilateral carotid artery stenosis (BCAS) have been reported to significantly increase." (PMID 38327496, 2024).
ascariasis (2 papers, 2016 to 2024). An infection that is caused by the roundworm Ascaris lumbricoides, many cases of which remain asymptomatic. "Furthermore, the study found elevated levels of IL-1β and TNFα, indicating that ascariasis increases susceptibility to Aspergillus sp." (PMID 39591259, 2024). "Human ascariasis is characterized by a Th2 and regulatory immune response, although innate production of IL-5, IL-6 and TNF-α seems to play crucial role in the pathogenesis of experimental larval ascariasis." (PMID 26814713, 2016).
atrioventricular block (2 papers, 2009 to 2023). A heart block that is initiated in the atrioventricular node. "Moreover our case was not received anti-TNF and specifically infliximab therapy which are recognized causing atrioventricular block." (PMID 19196455, 2009).
autoimmune inner ear disease (2 papers, 2019 to 2025). A syndrome characterized by rapidly progressive sensorineural hearing loss (SNHL), that is often bilateral, and is potentially reversible. "In a prospective observational study, tumor necrosis factor-alpha levels in peripheral venous blood were compared between patients with autoimmune inner ear disease and sudden SNHL compared to controls and steroid responders compared with steroid nonresponders." (PMID 31781229, 2019).
autoimmune vasculitis (2 papers, 2016 to 2024). An autoimmune form of vasculitis. "Treatment for primary autoimmune vasculitis consists of corticosteroids and other immunosuppressive agents such as cyclophosphamide, rituximab, azathioprine, and TNF-alpha inhibitors whereas treatment for infection-related vasculitis is aimed at treating the underlying infection." (PMID 38916001, 2024).
autonomic neuropathy (2 papers, 2022 to 2023). An inherited or acquired peripheral neuropathy affecting the autonomic nervous system. "This study demonstrated a relatively high prevalence of peripheral (especially autonomic) neuropathy and verified some risk factors for the development of peripheral somatic neuropathy in asymptomatic patients with severe form of CD on anti-TNFα biological therapy." (PMID 37967139, 2023). "Factors of relevance described in the literature in DM include advanced glycated end-product deposition in the myocardium, myofibroblast ‘switching’, autonomic neuropathy, inflammation via TNF-alpha and IL-1b, renin–angiotensin system activation, and blood glucose levels." (PMID 35596784, 2022).
avian influenza (2 papers, 2019 to 2022). Infection of domestic and wild fowl and other birds with influenza A virus. "SwIV and highly pathogenic avian influenza (HPAI) induced more TNFα when compared to huIV and low pathogenic avian influenza (LPAI)." (PMID 30862035, 2019). "In contrast, H5N6 VLPs not only elicited higher neutralizing antibody titers, ranging from 640 to 1280, but also induced higher IL-2, IL-4, IL-5, IFN-γ and TNF production, thus indicating that H5N6 VLPs may be a potential vaccine candidate for broad-spectrum H5Nx avian influenza vaccines." (PMID 35632667, 2022).
benign breast disease (2 papers, 2015 to 2016). "Significant levels were identified in EC-CFUs from benign breast disease patients treated with 10 pg/ml of TNF-α (n = 5, 1.875 ± 0.295, p = 0.0317) in comparison with those treated with 1 pg/ml (n = 5, 1.233 ± 0.0753)." (PMID 27881867, 2016). "In the EC-CFUs from healthy controls and benign breast disease patients, higher levels of caspase 3 activities were demonstrated after incubation of TNF-α at 1 and 10 pg/ml compared to those who received no TNF-α treatment." (PMID 27881867, 2016).
benign breast tumors (2 papers, 2023 to 2024). "The correlation between IL-6 and TNF-α was more significant in patients with benign breast tumors than in those with GLM patients, which is worth noting and requires further research." (PMID 37817809, 2023).
benign ovarian tumor (2 papers, 2017 to 2023). "In contrast, TLR agonist-induced TNFα production was largely unaffected by peritoneal fluid from these benign ovarian tumours." (PMID 28410380, 2017).
bilateral progressive sensorineural hearing loss (2 papers, 2022 to 2025). "We identified a ZNF334 truncation mutation (p.Thr399fs) in a rare case of late-onset cold-induced autoinflammatory disease with elevated TNF-α, IL-1β, IL-6, and extracellular heat shock protein 90 (eHsp90) plasma levels and progressive sensorineural hearing loss." (PMID 41168503, 2025).
bleeding (2 papers, 2019 to 2022). "To confirm the effect of TXA on the Heme/MyD88/TNF axis after CNS bleeding as previously reported, we performed a Western blot analysis for MyD88 and NF-κB p65." (PMID 31358003, 2019).
bone metabolism disorders (2 papers, 2024 to 2025). "Proinflammatory cytokines, including TNFα, IL6, IL18, IL17, and CRP appear to activate osteoclasts and osteoblasts, leading to bone metabolism disorders." (PMID 38272859, 2024).
bronchial pneumonia (2 papers, 2022 to 2024). "In bronchial pneumonia, the flavonoids group decreased the time to symptoms disappearance, the level of interleukin-6 (IL-6), interleukin-8 (IL-8), and tumor necrosis factor-α (TNF-α)." (PMID 35252093, 2022).
Budd-Chiari Syndrome (2 papers, 2012 to 2015). "Veno-occlusive disease was accompanied by a significant increase in levels of IL-6, IL-8 and TNF-α.Graft-versus-Host disease was associated with a significant increase of IL-10, sIL-2R, IL-6 and TNF-α, depending on the respective stage or grade." (PMID 26315105, 2015).
Burkholderia Infections (2 papers, 2013 to 2017). Infections with bacteria of the genus BURKHOLDERIA. "Thus, TNF-α appears to play a dual role in regulation of both protection and susceptibility to Burkholderia infection." (PMID 23508691, 2013). "Key cytokines including MCP-1, INF-γ, and TNF-α also are required for protective immunity to Burkholderia infection." (PMID 23508691, 2013). "Since Nramp1 is well-known to have pleiotropic effects on release of pro-inflammatory cytokines, including IL1-β, TNF-α and IL-6, in response to bacterial uptake, we also investigated the effects of Nramp1 on production of pro-inflammatory cytokines in response to Burkholderia infection." (PMID 28848712, 2017). "Unlike TNF-α, the role of IFN-γ in protection from Burkholderia infection is unambiguous and IFN-γ is obviously a key protective cytokine." (PMID 23508691, 2013).